MIR376C (microRNA 376c)
Synonyms: hsa-mir-368; hsa-mir-376c; MIR368; MIRN368; MIRN376C; miRNA368; mir-376c
Gene: MicroRNA gene on chromosome 14 (101,039,690 to 101,039,755, forward strand). Ensembl gene ENSG00000283279.
Gene Ontology:
Biological process: miRNA-mediated post-transcriptional gene silencing
Cellular component: RISC complex